COL5A2 (collagen type V alpha 2 chain)
Description:
Type V collagen is a member of group I collagen (fibrillar forming collagen). It is a minor connective tissue component of nearly ubiquitous distribution. Type V collagen binds to DNA, heparan sulfate, thrombospondin, heparin, and insulin. Type V collagen is a key determinant in the assembly of tissue-specific matrices (By similarity).
Synonyms: EDSC; EDSCL2
Tractability: Antibody: its Gene Ontology location is reachable by antibodies, with high confidence; UniProt places it where antibodies can reach, with medium confidence; UniProt predicts a signal peptide or a membrane-spanning region. PROTAC: ubiquitination databases record sites on it. Other modalities: an approved drug acts on it.
Gene: Protein-coding gene on chromosome 2 (189,031,898 to 189,225,312, reverse strand). Ensembl gene ENSG00000204262.
Subcellular location: Secreted, extracellular space, extracellular matrix
Pathways (Reactome):
Extracellular matrix organization: Assembly of collagen fibrils and other multimeric structures; Collagen biosynthesis and modifying enzymes; Collagen chain trimerization; Collagen degradation; ECM proteoglycans; Fibronectin matrix formation; Integrin cell surface interactions; Non-integrin membrane-ECM interactions; Syndecan interactions
Developmental Biology: Developmental Lineage of Pancreatic Ductal Cells; NCAM1 interactions
Signal Transduction: MET activates PTK2 signaling; Signaling by PDGF
Disease: Attachment of bacteria to epithelial cells
Gene Ontology:
Molecular function: extracellular matrix structural constituent conferring tensile strength; extracellular matrix structural constituent; SMAD binding
Biological process: collagen fibril organization; eye morphogenesis; negative regulation of endodermal cell differentiation; skin development; animal organ development; system development
Cellular component: collagen type V trimer; extracellular matrix; collagen type XI trimer; endoplasmic reticulum lumen; extracellular region; collagen trimer; fibrillar collagen trimer
Genetic constraint (gnomAD): Loss-of-function variants: 10 observed, 159.93 expected, observed/expected ratio (o/e) 0.0625, 90% interval 0.038 to 0.11. The upper end of that interval is the gene's LOEUF score, 0.11, which puts it in group 1 of 6, group 1 being the genes least tolerant of losing a copy. Missense variants: 1,423 observed, 1,815.8 expected, observed/expected ratio (o/e) 0.78, 90% interval 0.75 to 0.82. Synonymous variants: 579 observed, 599.16 expected, observed/expected ratio (o/e) 0.97, 90% interval 0.9 to 1.03.
Gene-disease validity (ClinGen):
ClinGen rates the evidence that COL5A2 causes each of these diseases.
Ehlers-Danlos syndrome, classic type (autosomal dominant): Definitive. Ehlers-Danlos syndrome, classic type (cEDS) is a form of Ehlers-Danlos syndrome that affects the connective tissue and is characterized by skin hyperextensibility, widened atrophic scars and joint hypermobility.
Homologues: Orthologues: chimpanzee COL5A2 (99% identical), macaque COL5A2 (99% identical), pig COL5A2 (97% identical), rabbit COL5A2 (96% identical), dog COL5A2 (96% identical), guinea pig COL5A2 (95% identical), mouse Col5a2 (95% identical), rat Col5a2 (94% identical), tropical clawed frog col5a2 (82% identical), zebrafish col5a2a (70% identical). Paralogues in human: COL2A1 (64% identical), COL1A1 (59% identical), COL3A1 (54% identical), COL1A2 (52% identical), COL5A1 (41% identical), COL11A1 (41% identical), COL11A2 (39% identical), COL5A3 (38% identical), COL4A5 (36% identical), COL4A1 (36% identical), COL4A4 (35% identical), COL4A3 (34% identical), and 25 more.
Diseases named in the same sentence as COL5A2 in open-access papers:
COL5A2 is named in the same sentence as 108 diseases in open-access papers, as found by Europe PMC text mining. Sharing a sentence is not in itself a finding about the gene and the disease. The quoted sentences say what the papers report.
bladder cancer (26 papers, 2007 to 2025). "COL5A2 has been associated with prognosis in tongue cSCC, oesophageal cSCC, bladder cancer and ovarian cancer." (PMID 40386063, 2025). "COL5A2 is classified as a clinical biomarker for metastasis, such as gastric, colorectal, and bladder cancer, including osteosarcoma, and has been associated with the development of tumors in the immune system, proliferation, and angiogenesis." (PMID 35625426, 2022). "For example, COL5A2 has previously been found to be associated with tumorigenesis, pathological processes or prognosis of osteosarcoma, bladder cancer, and GC." (PMID 34899080, 2021). "A retrospective analysis of the gene expression profiles related to bladder cancer shows that COL5A2 is associated with the poor clinical prognosis and a low survival rate of patients with bladder cancer." (PMID 32819300, 2020). "COL5A2 is upregulated in colorectal and breast cancers and is associated with poor clinical outcome and poor survival rates in bladder cancer." (PMID 32986753, 2020). "COL5A2 was involved in osteosarcoma cell proliferation and invasion, provided new insights into cytostatic drug resistance of ovarian cancer, and represented early potential diagnostic biomarkers and therapeutic targets for bladder cancer." (PMID 34034744, 2021). "Moreover, overexpression of COL5A2 has been related to worse prognosis with potential association with invasion and dissemination in bladder carcinoma, or in osteosarcoma, as an effector of NKX2-2, among others." (PMID 33066614, 2020). "For example, in multiple cancers such as bladder cancer, gastric cancer and colorectal cancer, increased expression of Col5a2 was correlated with poor clinical outcomes and survival of patients." (PMID 35964009, 2022). "The expression level of COL5A2 can also effectively predict patient outcomes in multiple malignant tumors, including gastric cancer, bladder cancer and tongue squamous cell carcinoma." (PMID 34419075, 2021). "Lower COL5A2 expression indicates better overall survival in bladder cancer patients, suggesting that it is a prognostic biomarker." (PMID 32509452, 2020). "In addition, COL5A2 is involved in the occurrence and development of various malignancies, such as lung cancer, squamous cell carcinomas, bladder cancer, and colon cancer." (PMID 36263088, 2022). "A previous study investigating the relationship between collagen type V alpha 2 chain (COL5A2) expression and clinical outcome in bladder cancer patients observed that patients with lower expression of COL5A2 had better survival than those with higher expression." (PMID 35046456, 2022). "In bladder cancer, cases with low COL5A2 amounts show improved clinicopathological phenotypes." (PMID 34281542, 2021). "A retrospective analysis of bladder cancer gene expression data presented that COL5A2 in patients with bladder cancer and ischemic heart disease may possess important clinical significance." (PMID 33193601, 2020). "COL5A2 was reported to be correlated with poor clinical outcomes of bladder cancer patients, suggesting that it could serve as a cancer biomarker (Zeng, Liu, Liu, & Wang, 2018)." (PMID 31612481, 2020). "Compared with the normal bladder epithelial cell line (SV-HUC-1), the expression levels of 2 model genes (COL5A2 and SCG2) in bladder cancer cell lines (T24 and SW1710) were significantly elevated." (PMID 39995998, 2025). "MRNA expression levels of COL5A2 and SCG2 were considerably elevated in the bladder cancer cell strains (T24 and SW1710) relative to standard bladder epithelial cell strain (SV-HUC-1)." (PMID 39995998, 2025). "The expression levels of 5 model genes (COL5A2, JAG1, MSX1, OLR1, and STC) were significantly increased in bladder cancer cell lines (T24 and 5637) compared with the normal bladder epithelial cell line SV-HUC-1." (PMID 37988196, 2023).
bladder cancer (continued). "We investigated the expression levels of 5 model genes (COL5A2, JAG1, MSX1, OLR1, and STC) in normal bladder epithelial cell lines (SV-HUC-1) and bladder cancer cell lines (T24 and 5637)." (PMID 37988196, 2023). "Genes such as COL5A2, SVEP1, NID2, and MMP23B were responsible for the growth of many cancer types such as bladder cancer and mammary adenocarcinoma, but these genes may be involved in the pathogenesis of GBM." (PMID 31137733, 2019).
gastric cancer (26 papers, 2015 to 2025). A primary or metastatic malignant neoplasm involving the stomach. "For instance, a study on gastric cancer reported that COL5A2 expression was associated with tumor progression and immune infiltration, suggesting its potential as a prognostic biomarker and therapeutic intervention strategy." (PMID 40087784, 2025). "In particular, type V collagen alpha 2 (COL5A2) has been observed to be associated with gastric cancer progression since this was found to be upregulated in affected patients." (PMID 39769286, 2024). "SNAI2, a critical regulator of EMT, has been implicated in promoting EMT in gastric cancer by upregulating COL5A2 expression." (PMID 38872418, 2024). "It has been demonstrated that high COL5A2 expression promotes the proliferation and invasion of prostate cancer cells, is associated with poor prognosis in patients with gastric cancer, and promotes the proliferation of colon cancer cells by activating the Wnt/β-catenin signaling pathway." (PMID 35280775, 2022). "COL5A2 has been shown to play a direct role in cell proliferation of gastric cancer cells, where triggering the FAK/PI3K/Akt/mammalian Target Of Rapamycin (mTOR) signaling pathway." (PMID 39769286, 2024). "Through the data analysis of gastric cancer in the TCGA database, we found that the expression of COL5A2 in T1 stage was different from those in the T2–4 stages." (PMID 36447214, 2022). "Hub genes containing COL5A2, JAG1, TIMP1, FGFR1, PDFGA, VEGFA, and PTK2 were collected from the gene sets and were proven to be linked to the occurrence and development of gastric cancer." (PMID 35875363, 2022). "We elucidated the regulatory role of the pseudogenes/lncRNA-hsa-miR-200b-3p-COL5A2 network in gastric cancer progression and constructed a nomogram." (PMID 36447214, 2022). "In summary, the downregulation of hsa-miR-200b-3p mediated by overexpressed lncRNAs/pseudogenes leads to an increase in COL5A2 expression, which leads to the progression of gastric cancer." (PMID 36447214, 2022). "As members of the collagen family, both COL3A1 and COL5A2 had significant value in the prognosis of gastric cancer." (PMID 33828526, 2021). "In order to verify the effect of COL5A2 on the migration of gastric cancer cells in vivo, SGC-7901 cells were injected into two groups of nude mice through tail vein." (PMID 33739392, 2021). "Scratch and migration experiments showed that knockdown of COL5A2 decreased the migration ability of gastric cancer cells compared with the control group." (PMID 33739392, 2021). "In summary, we uncovered the prognostic value of COL3A1/FBN1/COL5A2/SPARC-mir-29a-3p-H19 ceRNA network in gastric cancer." (PMID 32742441, 2020). "Besides, COL5A2 is a prognostic biomarker in gastric cancer, highlighting its correlation with immune infiltrates, such as CD4+ and CD8 + T cells, macrophages and plasmacytoid dendritic cells." (PMID 38789829, 2024). "Many studies have demonstrated that COL5A2 is differentially expressed in various tumors, such as gastric cancer, esophageal squamous cell carcinoma, non-small cell lung cancer (lung squamous carcinoma and lung adenocarcinoma), and colorectal cancer, and is associated with poor prognosis." (PMID 38789829, 2024). "Previous bioinformatics analysis has demonstrated that COL5A2, COL10A1, and COL11A1 may be used as a diagnostic or prognostic biomarker for tumors such as gastric cancer, breast carcinoma, and non-small-cell lung cancer." (PMID 37082197, 2023). "Together, these studies illuminate that COL1A1 and COL5A2 may not only be reliable biomarkers of gastric cancer cell proliferation and metastasis, and also key predictors of poor prognosis in patients with gastric cancer." (PMID 36471693, 2022). "The StarBase database was used to predict that 3 pseudogenes and 7 lncRNAs might inhibit the hsa-miR-200b-3p-COL5A2 axis in gastric cancer." (PMID 36447214, 2022).
gastric cancer (continued). "Scratch and migration experiments confirmed that overexpression of COL5A2 could promote the migration of gastric cancer cells, compared with the control group." (PMID 33739392, 2021). "Therefore, COL5A2 was selected as a prognostic marker for gastric cancer." (PMID 36447214, 2022). "Therefore, COL5A2 may be a potential biomarker and therapeutic target for gastric cancer." (PMID 36447214, 2022). "The results showed that DAZ1, WIPF3, RBPMS2, and NOVA1 were low expressed in gastric cancer (P<0.05), and KIAA0101 and COL5A2 were highly expressed (P<0.05)." (PMID 34234866, 2021). "Besides, high expression of five genes, POSTN, COL5A2, COL1A1, FN1, and MMP2, was revealed by Kaplan–Meier survival curve analysis to suggest a poor prognosis for gastric cancer patients." (PMID 37461041, 2023). "First, we found that COL5A2, COL12A1, BGN and THBS2 were highly expressed in gastric cancer." (PMID 36447214, 2022). "The results showed that 8 up-regulated genes (FN1, COL3A1, FBN1, BGN, COL5A2, THBS2, COL5A1 and SPARC) and 1 down-regulated gene (ATP4A) may be the central genes in gastric cancer." (PMID 32742441, 2020). "Moreover, expression of COL5A2 and COL11A1 was associated with colorectal carcinogenesis showing that COL5A2 was co-expressed with COL11A1 in colorectal tumor samples, but not in normal colon epithelia; however, it remains unknown which miRNA(s) regulate their expression in gastric cancer." (PMID 25860484, 2015). "Additionally, to investigate the clinical relevance of the target gene expression in gastric cancer, we examined their expression levels at different stages of TCGA gastric cancer samples and observed significantly higher expression of SERPINE1, COL5A2, SEMA3C and LOXL2 in more aggressive stages." (PMID 36307405, 2022).
Ehlers-Danlos syndrome (16 papers, 2010 to 2025). The Ehlers–Danlos syndromes (EDS) are a clinically and genetically heterogeneous group of heritable connective tissue disorders (HCTDs) characterized by joint hypermobility, skin hyperextensibility, and tissue fragility. "Heterotrimeric collagen V fibrils regulate the diameter of fibrillar collagen I fibrils in skin and mutations in COL5A1 and COL5A2 can result in classic Ehlers-Danlos syndrome, characterized by fragile skin, hyperextensible skin and impaired wound healing." (PMID 38559576, 2024). "Mutations in COL5A2 or COL5A1 account for over 90% of the cases of the classic Ehlers-Danlos syndrome, characteristic for joint hypermobility." (PMID 35588128, 2022). "COL5A1 and COL5A2 are involved in encoding type V collagen, and its mutation is related to Ehlers-Danlos syndrome." (PMID 35872873, 2022). "Mutations in COL5A2 have been linked to Ehlers-Danlos syndrome which is a group of disorders affecting connective tissues supporting the bones, skin, blood vessels and many organs and tissues throughout the body." (PMID 33888815, 2021). "It has been proved that the mutation of COL5A1 and COL5A2 leads to Ehlers-Danlos syndrome, a connective tissue disorder." (PMID 33860039, 2021). "Mutations in COL5A1 and COL5A2 genes resulting in haploinsufficiency or structural modifications of type V collagen are common causes for classical Ehlers-Danlos Syndrome (types I and II)." (PMID 28346524, 2017). "Defects in the proα1(V)- or the proα2(V)-chain, encoded by COL5A1 and COL5A2 respectively, lead to classic Ehlers-Danlos Syndrome (EDS), formerly known as EDS type I, “gravis” (MIM# 130000) and EDS type II, “mitis” (MIM# 130010)." (PMID 21611149, 2011). "For instance, mutations in COL1A2, COL3A1, and COL5A2 human genes (identified as hub genes in the present research) are at least in part the genetic basis of the Ehlers-Danlos syndrome: a systemic connective tissue disorder caused by defects in fibrillar collagen deposition." (PMID 35874513, 2022). "Defects in type V collagen due to mutations in COL5A1 and COL5A2 are the cause of the classical type (types I and II) of the heritable connective tissue disorder Ehler-Danlos syndrome that confers an increased risk for PTD if the fetus is affected, especially from pPROM." (PMID 22208904, 2011). "Three genes (COL3A1, COL5A2, and SLC40A1) have also been associated with autosomal dominant disorders (Ehlers-Danlos syndrome classical type, hemochromatosis type 4, and muscle hypertrophy)." (PMID 30911334, 2019). "Col5a2, a gene previously not specifically linked to MI response but responsible for the classic type of Ehlers-Danlos syndrome, was found to have many and strong co-expression associations within this community (11 connections with ρ > 0.85)." (PMID 23574622, 2013). "Other possible candidates are the type V collagen genes COL5A1and COL5A2 involved in Ehlers-Danlos syndrome (EDS), fibrillin-1 gene (FBN1) responsible for Marfan syndrome, PAX6 associated with aniridia and FOXC1 associated with abnormal ocular development." (PMID 20485516, 2010). "Moreover, patients suffering from classic Ehlers-Danlos syndrome, a rare connective tissue disorder mainly caused by mutations in COL5A1 or COL5A2, do not appear to show ventricular malformations." (PMID 23574622, 2013).